HDAC6 (histone deacetylase 6)
Diseases named in the same sentence as HDAC6 in open-access papers (continued):
Sharing a sentence is not in itself a finding about the gene and the disease.
glioblastoma (36 papers, 2014 to 2025). The most malignant astrocytic tumor (WHO grade IV). "Tubastatin A is the most effective and promising specific HDAC6 inhibitor against cancer and it has shown antitumor activity in glioblastoma." (PMID 41471109, 2025). "In conclusion, this study reveals a novel interplay between KYNU and HDAC6 in regulating complement gene expression and glioblastoma cell viability." (PMID 40843669, 2025). "Pharmacological inhibition of histone deacetylase 6 (HDAC6) prevents the progression of glioblastoma multiforme, an aggressive form of cancer affecting the central nervous system with a poor prognosis." (PMID 39717752, 2024). "It has to be remarked that, to date, very few papers investigated the role of HDAC6 in glioblastoma ontogeny." (PMID 39595195, 2024). "ACY-1215 (ricolinostat, a specific HDAC6 inhibitor) suppresses glioblastoma growth by inhibiting TGF-β/SMAD2 signaling to decrease the expression of p21." (PMID 36834846, 2023). "Azaindolyl sulfonamide, a potent HDAC6 inhibitor, induced G2/M arrest and senescence in temozolomide-resistant glioblastoma cells." (PMID 36834846, 2023). "The downregulation of HDAC6 inhibited the proliferation and migration of glioblastoma cell lines and the sonic hedgehog (shh) pathway, and decreased autophagy." (PMID 36834846, 2023). "Sun Brain Statistics disclosed HDAC6 overexpression in glioblastoma tissues compared with normal tissues and the fold change was 3.221 (p = 6.66E-13)." (PMID 35359455, 2022). "J22352, an inhibitor of HDAC6, promoted HDAC6 degradation and induced anti-cancer effects by inhibiting autophagy in glioblastoma." (PMID 36076996, 2022). "HDAC6 was reported to promote glioblastoma proliferation by increasing the expression of mitogen activated protein kinase 7 (MKK7) and enhancing Jun N-terminal kinase (JNK) activity." (PMID 36076996, 2022). "High levels of TDP-43 and HDAC6 were shown to predict low relapse-free survival in patients with glioblastoma." (PMID 36076996, 2022). "Azaindolylsulfonamide, an HDAC6 inhibitor, was shown to target the long non-coding RNA LINC00461, causing cell-cycle arrest and suppressing the proliferation of glioblastoma cells." (PMID 36076996, 2022). "HDAC6 also promoted the proliferation of glioblastoma by increasing the levels of DNA damage response genes such as DNA repair protein 51 (RAD51) and checkpoint kinase 1 (CHEK1)." (PMID 36076996, 2022). "With these data, we have been able to determine that the glioblastoma cell lines used in our study exhibit HDAC6 overexpression, which we believe leads to defective ciliogenesis." (PMID 34073238, 2021). "To corroborate this fact, we studied the expression of HDAC6 both at the mRNA level and at the protein level, obtaining a similar result and confirming the overexpression of HDAC6 in glioblastoma." (PMID 34073238, 2021). "HDAC6 silencing decreases cell proliferation, clonogenicity, and migration in glioblastoma cell lines; restores the primary cilium, reverts the EMT phenotype, and inhibits autophagy; and also inhibits the Shh pathway in U87MG cells." (PMID 34073238, 2021). "RNA was extracted from frozen samples of healthy brains and glioblastomas, and a reverse transcription (RT) and a real-time PCR (qPCR) were performed to study the expression of HDAC6 in those samples." (PMID 34073238, 2021). "In this study, we aimed to evaluate the role of HDAC6 in the pathogenesis of glioblastoma, as HDAC6 is the most overexpressed of all HDACs isoforms in this tumor." (PMID 34073238, 2021). "One of the effects of HDAC6 silencing in glioblastoma is the inhibition of cell proliferation and, therefore, the inhibition of tumor growth." (PMID 34073238, 2021). "Another recently reported highly selective HDAC6 inhibitor is J22352, shown to exert anticancer effects in glioblastoma." (PMID 34944907, 2021).
glioblastoma (continued). "Another study carried out in tissues of healthy and tumor controls demonstrated that HDAC6 appeared to be the isoform of HDAC most highly overexpressed in glioblastoma." (PMID 34073238, 2021). "HDAC6, as well as mesenchymal and autophagic markers, are overexpressed in glioblastoma samples and cell lines." (PMID 34073238, 2021). "More research is needed to finally figure out a molecular mechanism that regulates the primary cilium formation/differentiation by HDAC6 in glioblastoma cells." (PMID 34073238, 2021). "Confirming the data obtained in tissue samples, we observed that both HDAC6 and mesenchymal markers were overexpressed in cell lines derived from glioblastoma." (PMID 34073238, 2021). "Histone deacetylase 6 (HDAC6) is an emerging therapeutic target that is overexpressed in glioblastoma when compared to other HDACs." (PMID 33915983, 2021). "Concordantly, a highly selective HDAC6 inhibitor induces the accumulation of autophagic vacuoles and abrogates the autophagic flux by inhibiting autophagosome–lysosome fusion in glioblastoma cells." (PMID 35008169, 2021). "HDAC6 silencing also induced the appearance of the primary cilium in a subpopulation of glioblastoma cell lines, demonstrating the relationship between HDAC6 and the primary cilium." (PMID 34073238, 2021). "As a result, we obtained that HDAC6 was three times more expressed in glioblastoma tissue than in tissues of the temporal area of healthy brains (p = 0.0038)." (PMID 34073238, 2021). "From these results, we can assume that HDAC6 fulfills several functions in the development and growth of glioblastoma." (PMID 34073238, 2021). "In several types of cancer cells such as bladder cancer, malignant melanoma and glioblastoma, HDAC6 is frequently over-expressed." (PMID 33262941, 2020). "For example, J22352 as a highly HDAC6-selective inhibitor suppresses the proliferation as well as migration of glioblastoma through promoting the proteolysis degradation of HDAC6 and resulting in anti-cancer effect by inhibiting autophagy." (PMID 33262941, 2020). "In conclusion, our data reveal the efficacy of a novel HDAC6 inhibitor in glioblastoma preclinical setting." (PMID 32488056, 2020). "HDAC6 inhibition leads to remarkable acetylation of α-tubulin, thereby impairing cytoskeletal organization in glioblastoma cells." (PMID 31013819, 2019). "Conversely, inactivation or suppression of HDAC6 induces apoptosis, inhibits cell proliferation, delays spheroid formation, and renders glioblastoma cells more sensitive to temozolomide." (PMID 31013819, 2019). "This upregulation of HDAC6 protein facilitates the cell proliferation and spheroid formation of glioblastoma cells and renders them resistant to temozolomide." (PMID 31013819, 2019). "Recent studies have shown that HDAC6 protein enhances cell proliferation and imparts temozolomide resistance in glioblastoma." (PMID 31013819, 2019). "A growing number of studies have reported abnormal expression profiles of HDAC6 in different types of tumors such as glioblastoma, oral squamous cell carcinoma, breast cancer, ovarian cancer, and model organisms." (PMID 31013819, 2019). "Further, it has been shown that HDAC6 protein is upregulated in glioblastoma tissues and its cell lines." (PMID 31013819, 2019). "Inhibition of HDAC6 leads to significant α-tubulin acetylation, thereby impairing cytoskeletal organization in glioblastoma cells." (PMID 30302275, 2018). "We propose the mechanism of action of sahaquine to implicate HDAC6 inhibition together with suppression of epidermal growth factor receptor and downstream kinase activity, which are prominent therapeutic targets in glioblastoma multiforme." (PMID 30302275, 2018). "Histone deacetylase 6 promoted glioblastoma growth through the MAP2K7/JNK/C-Jun signaling pathway." (PMID 38698487, 2024).
glioblastoma (continued). "It has been reported that, together with HDAC4, HDAC6 promotes double-strand breaks (DSBs) repair in glioblastoma, as interfering with their translation promotes radiosensitivity in the U87MG and U251 GBM cell lines but not in normal astrocytes or cortical neurons." (PMID 39595195, 2024). "HDAC6 is a guardian of irradiation-induced DNA damage and stemness in glioblastoma." (PMID 36951571, 2023). "A high level of HDAC6 can predict the poor prognosis of glioblastoma patients." (PMID 36076996, 2022). "After having detected the overexpression of HDAC6 and mesenchymal and autophagic markers in tumor samples, we studied the expression levels of HDAC6 and of the mesenchymal markers Snail and Slug in our glioblastoma cell lines by RT-qPCR and western blot." (PMID 34073238, 2021). "Our HDAC6-silencing experiments induced a decrease in Snail and Slug mesenchymal markers in the glioblastoma cell lines at the mRNA level, although, at the protein level, this decrease only occurred in the cell lines with more evident mesenchymal phenotypes: LN405 and T98G." (PMID 34073238, 2021). "As our study has been done with glioblastoma cell lines that express HDAC6, we can estimate that the results obtained would be of interest when applied to glioblastomas that present non-mutated EFGR." (PMID 34073238, 2021). "In the same year, other authors observed that the balance of HDAC6-VCP/p97 (increasedHDAC6levels and decreased VCP/p97 levels) was positively associated with temozolomide resistance in glioblastoma and that the reversal of the ratio of HDAC6-VCP/p97 represented a potential therapeutic strategy." (PMID 34576340, 2021). "We have also demonstrated these effects after HDAC6 silencing in glioblastoma." (PMID 34073238, 2021). "After having verified that HDAC6 is overexpressed in glioblastoma, we wanted to silence its expression using a siRNA to infer the effects this protein might contribute to the development of this tumor." (PMID 34073238, 2021). "As a result, we obtained that the silencing of HDAC6 inhibits cell growth, which makes us think that, by promoting proliferation, HDAC6 has an oncogenic role and therefore may be a therapeutic target in glioblastoma." (PMID 34073238, 2021). "Furthermore, the inhibition of HDAC6 not only decreased the proliferation of tumor cell lines but also their clonogenic capacity, demonstrating its oncogenic potential in glioblastoma." (PMID 34073238, 2021). "HDAC6 silencing inhibited proliferation, migration, and clonogenicity of glioblastoma cell lines." (PMID 34073238, 2021). "To verify this fact, we performed immunohistochemistry against HDAC6 in paraffin sections of healthy brain tissue and of tumor tissue, and we detected overexpression of HDAC6 in glioblastoma, showing a cytoplasmic staining, which is consistent with the literature studied." (PMID 34073238, 2021). "Glioblastoma (GBM) growth relies on glutamine synthetase (GS), which is stabilized by histone deacetylase 6 (HDAC6) and deubiquitinated by ubiquitin‐specific peptidase 9, X‐linked (USP9X)." (PMID 40162736, 2025). "A high level of HDAC6 has been reported in patients with glioblastoma multiforme (GBM) and in a subset of human gastric cancer cells." (PMID 36076996, 2022). "As a whole, we may conclude that HDAC6 seems to be a good target for glioblastoma treatment." (PMID 34073238, 2021). "Therefore, we believe that if we silence HDAC6, we could be able to restore the presence of the primary cilium in the glioblastoma cell lines." (PMID 34073238, 2021). "As we have seen in the comparison between cell lines and between healthy and tumor brain tissues, HDAC6 is overexpressed in glioblastoma, and this overexpression could lead to a decrease in acetylated α-tubulin levels and, consequently, to the absence of primary cilium in glioblastoma cell lines." (PMID 34073238, 2021).
glioblastoma (continued). "In addition, these tumors present overexpression of HDAC6, like glioblastoma, which reinforces the hypothesis that the primary cilium disappears due to overexpression of HDAC6." (PMID 34073238, 2021). "Sahaquine, a selective HDAC6 inhibitor, reduced the level of p-glycoprotein and EGFR activity and enhanced the sensitivity of glioblastoma to anti-cancer cancer drugs such as TMZ, quercetin, and buthionine sulfoximine." (PMID 36076996, 2022). "A high level of HDAC6 and the activation of the TGF-β/Smad pathway promoted glioblastoma progression." (PMID 36076996, 2022). "The downregulation of HDAC6 was shown to inhibit the proliferation and migration of glioblastoma cell lines, and ACY-1215 (Ricolinostat, a specific HDAC6 inhibitor) inhibits glioblastoma growth." (PMID 36076996, 2022). "Very recently, a work has been published which investigates not only the lncRNAs enriched in stem-like and chemo-resistant glioblastoma cells, but also those whose expression is affected by the selective inhibition of HDAC6 (Histone Deacetylase 6) through azaindolylsulfonamide (MPT0B291)." (PMID 36768150, 2023). "This confirms that HDAC6 silencing decreases autophagy in these glioblastoma cell lines, although we do not know if this is due to the fact that silencing inhibits autophagosome formation or inhibits the onset of autophagy." (PMID 34073238, 2021). "Since both HDAC6 and HDAC4 have been shown to facilitate DNA damage repair in glioblastoma, the synthetic interaction between HDAC4 and HDAC6 with MELK could indicate a role for MELK in DNA damage as well." (PMID 34550356, 2021). "We have also observed that HDAC6 inhibition decreases the levels of EMT-TFs Snail and Slug in mesenchymal glioblastoma cell lines and increases the expression of acetylated α-tubulin, the target of HDAC6 and possible epithelial marker, in the three cell lines used in the study." (PMID 34073238, 2021). "The increased expression of acetylated α-tubulin after HDAC6 inhibition resulted in the appearance of structures similar to the primary cilium in glioblastoma cells, structures that are not present at baseline." (PMID 34073238, 2021). "HDAC6-selective inhibitors, tubastatin A, CAY10603, and ACY1215 inhibited cell proliferation and induced apoptosis of U-87MG, U251, and A172 cells by inhibiting HDAC6 34 and HDAC inhibitors sensitized glioblastoma cells to TMZ and radiotherapy 34, 39-43." (PMID 33162824, 2020). "Concluding, we did not detect the presence of HDAC6 in NHA cells and, therefore, our glioblastoma cell lines certainly present HDAC6 overexpression." (PMID 34073238, 2021).
colon cancer (34 papers, 2011 to 2025). "Inhibition of HDAC6 with tubacin has been reported to cause Ku70 acetylation and c-Flip degradation in colon cancer cells." (PMID 29795376, 2018). "We find that the high levels of HDAC6 expression are associated with activated K-ras mutant in colon cancer patients." (PMID 26848526, 2016). "We find that activated K-ras mutants are associated with the high level of HDAC6 in colon cancer patients." (PMID 26848526, 2016). "In colon cancer, HDAC6 expression is high and associated with poor prognosis." (PMID 37072452, 2023). "However, the mechanisms of HDAC6 in the colon cancer microenvironment, especially those underlying the effect on macrophage polarization, are still unclear." (PMID 36270986, 2022). "To test the efficacy of the selective HDAC6 inhibitor ITF3756 in colon cancer cells, we first evaluated its effects on cell viability and morphology in HCT116 and HT29 CRC cell lines." (PMID 41458974, 2025). "Overall, these results reveal a particular antitumor efficacy of the selective HDAC6 inhibitor in combination with BTZ in colon cancer cells and suggest that inhibiting lipogenesis is a useful tool to further increase the synergistic effectiveness." (PMID 41458974, 2025). "The knockdown of either ONECUT3 or HDAC6 in colon cancer cells led to a marked increase in the acetylation level of HIF-1α." (PMID 40032849, 2025). "Considering the involvement of HDAC6 in lipid metabolism, the original idea was to block HDAC6 to clarify the effects on lipogenesis in colon cancer cells." (PMID 41458974, 2025). "AKAP12 is involved in promoting colon cancer metastasis via HDAC6-dependent AKAP12 deacetylation and ubiquitination mediated degradation." (PMID 38365849, 2024). "It has been reported that colon cancer specimens with high HDAC6 expression show increased infiltration of immunosuppressive M2 macrophages that can be attributed to HDAC6 activity." (PMID 38258065, 2023). "In this study, we investigated the role of HDAC6 in promoting macrophage M2 polarization in colon cancer." (PMID 36270986, 2022). "It has been reported that high HDAC6 expression indicates a poor colon cancer prognosis and can affect the proliferation and motility of colon cancer cells." (PMID 36270986, 2022). "The knockdown of HDAC6 inhibited the release of sIL-6R in colon cancer cells, thereby inhibition M2-like macrophage polarization." (PMID 36270986, 2022). "Further analysis demonstrated that HDAC6 in colon cancer cells promoted the polarization of M2 macrophages by regulating sIL-6R release." (PMID 36270986, 2022). "We found that phosphorylated TAK1 is positively correlated with HDAC6 and infiltration ratio of M2 macrophages in colon cancer tissues." (PMID 36270986, 2022). "Our findings reveal an underlying mechanism the HDAC6-mediated deacetylation of TAK1 regulation of sIL-6R release and suggest a promising strategy for inhibiting the development of colon cancer." (PMID 36270986, 2022). "To determine the possible pathway by which HDAC6 affects macrophage polarization in the colon cancer microenvironment, we used a human inflammatory antibody array kit to analyze the culture medium of HCT116 cells exposed to different treatment conditions." (PMID 36270986, 2022). "This study enhances our understanding of the functions and mechanisms of HDAC6 in human colon cancer immune microenvironment and provides a series of potential novel therapeutic targets for colon cancer treatment." (PMID 36270986, 2022). "Our study showed that the infiltration ratio of M2 macrophages was increased in colon cancer tissues with high HDAC6 expression." (PMID 36270986, 2022). "To further explore the effect of HDAC6 on macrophage polarization, we utilized an in vitro co-culture model of stable HDAC6-knockdown colon cancer cells and macrophages from healthy donors." (PMID 36270986, 2022).